TSHR (thyroid stimulating hormone receptor)
Diseases named in the same sentence as TSHR in open-access papers (continued):
Sharing a sentence is not in itself a finding about the gene and the disease.
thyroid cancer (continued). "The TSH‐CAR‐T cells demonstrate effective antitumor activity against TSHR‐positive differentiated thyroid cancer (DTC) cell lines in vitro, accompanied by cytokine release (IFNγ, IL‐2) and robust proliferation." (PMID 40985353, 2025). "Our finding indicates the feasibility of employing TSH targeting TSHR via CAR‐T cells for treating advanced thyroid cancer, presenting a new therapeutic strategy for DTC patients facing recurrence, metastasis, and radioactive iodine therapy resistance." (PMID 40985353, 2025). "The persistent expression of TSHR in DTC makes it an ideal candidate for targeted thyroid cancer therapy, with particular potential in the treatment of RAIR-DTC." (PMID 40532044, 2025). "TSHR expression is significantly positively correlated with the degree of differentiation in thyroid carcinoma." (PMID 40532044, 2025). "Epigenetic research shows TSHR’s role in thyroid cancer, highlighting its promoter region’s CpG dinucleotides." (PMID 39125979, 2024). "We focused on these miRNAs and TSHR methylation due to their significant roles in the pathogenesis of thyroid cancer." (PMID 39125979, 2024). "For instance, high levels of miR-146a have been correlated with hypermethylation of the TSHR promoter and reduced TSHR expression in thyroid cancer tissues." (PMID 39125979, 2024). "Research has shown that TSHR regulators have an interventional effect on experimental models of thyroid diseases such as GD and thyroid cancer." (PMID 38111381, 2023). "The correlation between TSHR expression and the two prognostic indicators indicated the role of TSHR in thyroid cancer." (PMID 37208644, 2023). "TSHR, as a differentiation indicator, had varying expression in different phenotypes of thyroid cancer." (PMID 37208644, 2023). "Current research has found that treatment with TSHR as a target through TSHR modulators has a positive effect on the treatment of autoimmune thyroid diseases and thyroid cancer." (PMID 38111381, 2023). "TSHR is differentially expressed in the thyroid cancer cells from normal tissues or benign diseases." (PMID 37208644, 2023). "TSHR was decreased in primary tumor and in any stages or histological subtypes when compared to normal group, indicating it was a strong biomarker of thyroid cancer." (PMID 37208644, 2023). "In conclusion, our study demonstrates the involvement of the autophagy signaling pathway in regulating TSHR/ETE/EMT in thyroid cancer cells." (PMID 38174330, 2023). "The results of GSEA and KEGG enrichment analysis demonstrate the involvement of the autophagy signaling pathway in regulating TSHR/ETE/EMT in thyroid cancer." (PMID 38174330, 2023). "The results revealed that the expression level of TSHR gene was lower in thyroid cancer tissues compared to normal tissues." (PMID 38174330, 2023). "Considering TSHR plays an important role in the occurrence and development of thyroid cancers, the in-depth study of TSHR is of great significance to exploring the diagnosis and treatment of thyroid cancers." (PMID 36694763, 2023). "There was a significant difference in the expression level of the TSHR gene between normal thyroid cells and differentiated thyroid cancer cells." (PMID 38174330, 2023). "Thyroid-stimulating hormone (TSH) accelerates genomic instability and angiogenesis in thyroid cancer by binding to the TSH receptor (TSHR), and a similar role of TSH is expected in other cancers." (PMID 38275375, 2023). "In thyroid cancer, TSHR expression was reduced in primary tumor and in any stages or histological subtypes, indicating its role as a biomarker." (PMID 37208644, 2023). "Studies have shown that the expression of TSHR is positively correlated with the differentiation degree of thyroid cancer." (PMID 36694763, 2023). "A significant association was observed between thyroid stimulating hormone receptor (TSHR) gene methylation and positive BRAF V600E mutation cases in thyroid cancer." (PMID 36975440, 2023).
thyroid cancer (continued). "Hypermethylation of TSHR gene, which leads to TSHR expression silencing, plays an important role in the pathogenesis of thyroid cancer." (PMID 36013156, 2022). "In this report, we showed a relapsed and refractory thyroid cancer patient treated with TSHR + CD19 CAR-T, a combination of two 2nd generation CAR-T molecules targeting both TSHR and CD19." (PMID 36138444, 2022). "The role of TSHR is established in well-differentiated thyroid cancers, where treatment with T4 to suppress TSH secretion from the hypophysis, in order to prevent TSHR activation, is the mainstay of treatment." (PMID 35160139, 2022). "Since most thyroid cell lines have lost their TSHR expression, we established a TSHR-positive target cell line by transducing the full-length TSHR gene with a luciferase reporter into the thyroid cancer cell line 8505c (8505c-TSHR)." (PMID 35252208, 2022). "Based on a second-generation CAR construct we investigated the feasibility of CAR-T cells in treating TSHR-positive thyroid cancers." (PMID 35252208, 2022). "The literature reported that nevirapine induced redifferentiation and RAI uptake via the TSHR/cAMP/CREB/PAX8 signal pathway in dedifferentiated thyroid cancer." (PMID 36142613, 2022). "Activation of the signaling cascades through TSHR is the pathway for carcinogenesis and a tumor growth promoter for thyroid cancer." (PMID 36013156, 2022). "In this study, we designed CAR-T cells targeting TSHR and evaluated their efficacy for the treatment of metastatic thyroid cancers both in vitro and in vivo." (PMID 35252208, 2022). "In vitro, 99mTc-TR1402 showed higher Kd than 99mTc-TR1401 and 99mTc-Thyrogen, confirming the higher affinity of the TR1402 for the TSHR expressed on human cell lines of thyroid cancer and explaining the high T/B ratios observed in vivo in dogs." (PMID 33926024, 2021). "Dogs often develop spontaneous thyroid cancers with histological features very similar to human follicular cancer, and expressing TSHR." (PMID 33926024, 2021). "The beneficial effects on GD and GO following administration of a monoclonal TSHR blocking antibody (TBAB) in a patient with thyroid cancer has recently been described." (PMID 34899596, 2021). "It is well known that the tumor necrosis factor alpha (TNF-α) receptors, folate receptor (FA), and thyroid-stimulating hormone receptor are highly expressed in thyroid cancer." (PMID 34944814, 2021). "To further validate that this promigration effect occurs through TSHR signaling, we transiently knocked down TSHR in thyroid cancer cells through siRNA." (PMID 34650915, 2021). "We already showed the possibility of imaging thyroid cancer using iodine-radiolabeled Thyrogen, but the study was limited by its relatively low affinity for TSHR." (PMID 33926024, 2021). "This allowed NIS, PAX-8, TTF-1, TTF-2, and TSHR gene expression to promote redifferentiation of thyroid cancers." (PMID 33995657, 2021). "The TSHR Thr632Ile, which was previously detected in thyroid cancer with uncertain significance, occurred in one Bethesda III/IV nodule." (PMID 34322384, 2021). "Referencing the Oncomine database, HT-related genes were discovered to be expressed in many different types of thyroid cancer, such as TSHR that is highly expressed in thyroid cancer." (PMID 34993154, 2021). "Our previous work has shown that TSHR expression levels play important roles in maintaining the differentiation of thyroid cancer cells." (PMID 34650915, 2021). "This study demonstrated that the radiolabeled superagonist rhTSH analogue (TR1402) has high affinity for the TSHR and, in dogs with spontaneous thyroid cancer, shows a high T/B ratio able to image an intrathyroidal cancer lesion." (PMID 33926024, 2021).
thyroid cancer (continued). "In particular, from several studies, it emerged that the TSHR is expressed in human thyroid cancers with different degrees of differentiation, which is confirmed by our IHC results on excised tumors from dogs affected by thyroid cancer." (PMID 33926024, 2021). "In tumor-targeting experiments, a focal uptake was observed in dogs with spontaneous intraglandular thyroid carcinoma, in which TSHR expression was confirmed by immunohistochemistry." (PMID 33926024, 2021). "Recent investigation has unraveled novel possibilities to directly target TSHR in thyroid cancers by using selective small molecule antagonists of TSHR." (PMID 32698392, 2020). "Our current understandings of the anticancer role of TSHR in thyroid cancer come mostly from the effectiveness of the therapeutic strategies manipulating the TSH/TSHR signaling pathways, for example, by administration of levothyroxine." (PMID 32698392, 2020). "This potential is supported by the success of the therapeutic strategies to manipulate TSH/TSHR function in treating differentiated thyroid cancer." (PMID 32698392, 2020). "For example, the expression levels of TSHR in the extra-thyroid cancers have to be high enough that the alteration of TSHR function induced by the cognate ligands is great enough to elicit the desired anticancer responses." (PMID 32698392, 2020). "Clinically useful strategies have been proposed to treat well-differentiated thyroid cancer, which harbors a higher density of TSHR." (PMID 32698392, 2020). "In the era of precision medicine and targeted therapy, TSHR has been proposed to be a potent target against thyroid cancer with several experimental compounds under development." (PMID 32698392, 2020). "A different novel strategy to control thyroid cancer includes targeting the TSHR with nano-liposomes coated with fragments of TSH and loaded with chemotherapeutic agents." (PMID 32472423, 2020). "Activation of the coupled signaling cascades through TSHR is considered the pivotal pathway for de novo carcinogenesis and/or tumor growth promoter for thyroid cancer." (PMID 32698392, 2020). "The cooperation of thyroid-stimulating hormone (TSH) and thyroid-stimulating hormone receptor (TSHR) is well-known to play an important role in the regulation of thyroid cancer cell proliferation." (PMID 31497532, 2019). "The effect of methylation alterations in thyroid carcinogenesis is demonstrated by downregulation of several tumor suppressors thyroid cancer cells, such as; TSHR, PTEN, RASSF1A, CDKN2A, DAPK1, TIMP3, ECAD, and RAP1GAP." (PMID 31835496, 2019). "Several studies have demonstrated an association of BRAFV600E mutation with reduced expression of thyroid iodide-metabolizing genes namely NIS, TSHR, TG in thyroid cancer and induces hypothyroidism." (PMID 30760304, 2019). "Some recent studies indicated to the epigenetic mechanisms contributing to promoter hypermethylation and silencing of thyroid stimulating hormone receptor (TSHR) gene have been documented in thyroid carcinomas." (PMID 32351906, 2019). "In the case of thyroid carcinomas, PCR-amplification of TSHR mRNAs in thyroid CTCs aid preoperative diagnosis and the monitoring of cancer relapse." (PMID 30781659, 2019). "Our data indicated LDR effectively recovered TSHR levels in thyroid carcinoma cells, perhaps decreasing STAT3-miRNA axis route accounting for the high undifferentiated phenotype." (PMID 30760304, 2019). "TSHR is a well-known thyroid-specific/abundant gene used clinically as a blood biomarker of thyroid carcinoma." (PMID 30781659, 2019). "Thyroid stimulating hormone receptor messenger RNA (TSHR-mRNA) is over-expressed in thyroid cancer patients, which indicates that TSHR-mRNA is a potential biomarker of thyroid cancer." (PMID 28036261, 2017). "In a mouse model of thyroid cancer genetic inactivation of TSH receptor attenuated tumor initiation suggesting that TSHR signaling cooperates with oncogenic BRAF." (PMID 28350298, 2017).
thyroid cancer (continued). "Because TSHR is mainly found in the thyroid, scientists have primarily focused on the role of TSHR in thyroid cancer progression." (PMID 28439256, 2017). "Several animal studies were performed to evaluate the role of TSHR signaling pathway and its relation with other oncogenes in thyroid cancer." (PMID 28117293, 2017). "Global sensitivity and specificity for the positivity of TSHR-mRNA in the thyroid cancer diagnosis is 72% and 82%." (PMID 28036261, 2017). "Thyroid and thyroid cancer cells specifically express TSHR-mRNA, increasing evidences have demonstrated that circulating TSHR-mRNA is involved in cancer diagnosis and prognosis." (PMID 28036261, 2017). "Overall, this meta-analysis indicates that circulating TSHR-mRNA is potential to be a biomarker for early-stage thyroid cancer diagnosis." (PMID 28036261, 2017). "Among these changes, methylation of TSHR is a common form of epigenetic alteration in thyroid cancers and correlates with the presence of other oncogenes." (PMID 28117293, 2017). "RT-PCR was applied for TSHR-mRNA detection, with histopathological examination as the gold standard for thyroid cancer diagnosis." (PMID 28036261, 2017). "Because TSHR-mRNA is over-expressed in thyroid cancer cells, the measurement of TSHR-mRNA in the circulation is very valuable for the diagnosis of thyroid cancer." (PMID 28036261, 2017). "The silencing of TSHR not only contributes to the development of thyroid carcinoma, but it desensitizes the thyroid tumors to radioiodine therapy through its interaction with sodium iodide symporter (NIS) in iodide uptake." (PMID 28117295, 2017). "Hyper methylation of the TSHR promoter is frequently found in thyroid carcinoma, although the promoter is un-methylated in normal and benign thyroid tumors." (PMID 28926589, 2017). "Hypermethylation of the TSHR promoter has been frequently found in thyroid carcinoma, while it is unmethylated in normal and benign thyroid tumors." (PMID 28117295, 2017). "Other studies also demonstrated that mRNA levels of NIS and TSHR were significantly lower in thyroid cancer tissues than in benign thyroid nodules or normal thyroid tissues." (PMID 26985248, 2016). "Many studies have reported that BRAFV600E mutation reduces the expression of thyroid iodine-handling genes (sodium iodide symporter, thyroid-stimulating hormone receptor, thyroglobulin, and thyroperoxidase) in thyroid cancer." (PMID 26857243, 2016). "We are developing an orally available small-molecule, allosteric TSH receptor (TSHR) agonist for follow-up diagnostics of patients with thyroid cancer." (PMID 27512388, 2016). "The higher expression of NIS, PDS, and TSHR in adolescents suggested a greater degree of differentiation of thyroid carcinomas in this age group." (PMID 27022395, 2016). "The TSHR is localized in the plasma membrane, and, thus, it has been proposed as a target to direct therapeutic compounds into thyroid cancer cells." (PMID 25705225, 2015). "As thyroid stimulating hormone receptor is the main hormone receptor responsible for growth and physiological functioning of thyroid gland, methylation of TSHr gene is believed to have an important role in the development of thyroid cancer." (PMID 26519197, 2015). "In this study, we investigated the methylation status of TSHr in well differentiated thyroid cancers using cytology derived DNA, hence its potential role as a diagnostic test in the discrimination of benign and malignant thyroid nodules." (PMID 26519197, 2015). "The eminent ratio of TSHr methylation in well-differentiated thyroid carcinoma against benign thyroidal nodules adduced that TSHr methylation status can be utilized as a tumor marker for well-differentiated thyroid cancer; however, it has a limited value." (PMID 26519197, 2015). "TSHR-Abs, however, are heterogeneous with regard to serum levels, binding characteristics to the TSHR, and biological effects in different thyroid cancer patients." (PMID 24115945, 2013).
thyroid cancer (continued). "For genes previously reported to be methylated in thyroid cancer, such as TSHR, or in other cancer types, such as RASSF1A, RAR-β2, p16, CDH1, DAPK, and MLH1, the methylation frequency in papillary thyroid cancer ranges from 15 to 33%." (PMID 24367375, 2013). "Given the functional relationship between THRA, THRB, TSHR and TRHR, we decided to evaluate the combined effect of common genetic variants of these genes on thyroid cancer susceptibility." (PMID 23781307, 2012). "Alterations in the genes of these receptors (THRA, THRB and TSHR) have been related to thyroid diseases, including thyroid cancer." (PMID 23781307, 2012). "Since 2001, their group has studied TSHR mRNA as a molecular marker of thyroid cancer that can be measured from the peripheral blood." (PMID 21969828, 2011). "TSHR-based therapeutic approaches, including small-molecule drugs, nanomaterials, and advanced immunotherapies, represent new avenues for treating thyroid cancer, particularly in patients who have developed resistance to traditional treatments, such as radioiodine therapy." (PMID 40532044, 2025). "In contrast, the recently reported novel orally active TSHR-targeting ligand A35 effectively inhibits human thyroid cancer proliferation and metastasis both in vitro and in vivo as a standalone treatment, showing minimal toxicity and strong potential as a lead compound for DTC therapy." (PMID 40532044, 2025). "There are nevertheless concerns that in vivo, nanomaterials containing TSH, the natural agonist of TSHR, may promote the proliferation and dissemination of thyroid cancer cells through mechanisms such as activation of the cAMP pathway." (PMID 40532044, 2025). "In thyroid cancer, HIF-1α, BRAF mutation, and TSHR signaling are considered key regulators." (PMID 41301693, 2025). "Preclinical evidence indicates that TSH may promote tumor progression, including proliferation, invasion, and immune evasion, particularly in thyroid cancer models exhibiting high TSHR expression." (PMID 41153734, 2025). "Therefore, the biological functions of TSHR in tumorigenesis and development must be clarified to develop a TSHR-targeted thyroid cancer therapeutic strategy." (PMID 40532044, 2025). "The combination of TSHR-targeted therapy with MAPK and PI3K pathway inhibitors may offer a novel approach for the treatment of thyroid cancer patients with low TSHR expression." (PMID 40532044, 2025). "Interestingly, both melanoma cells and thyroid cancer cells express the thyroid-stimulating hormone receptor." (PMID 39036614, 2024). "However, in the most common thyroid cancers due to BRAF, NRAS, and KRAS mutations, the role of TSHR signaling in the development and/or growth of these tumors has not been extensively studied." (PMID 39061242, 2024). "TSHR methylation is a vital epigenetic mechanism impacting the development of thyroid cancer." (PMID 39125979, 2024). "Studies have shown that certain miRNAs are differentially expressed in thyroid cancers and autoimmune thyroid diseases, which might correlate with changes in TSHR expression." (PMID 39125979, 2024). "The detection of thyroid-specific proteins, such as thyroglobulin (Tg), thyroid peroxidase (TPO) and thyroid stimulating hormone receptor (TSHR), may reflect the differentiation ability of thyroid cancer cells." (PMID 39349421, 2024). "Since iodine metabolism depends on TSHR, researchers think that aberrant methylation in promoter regions of TSHR may contribute to thyroid cancer development." (PMID 37560303, 2023). "With the binding of an antibody to an antigen, a series of downstream cascades are activated to induce apoptosis and inhibit proliferation of cancer cells, which is consistent with our results that more thyroid cancer cells suffer from apoptosis with the coupling of rhTSH to TSHR." (PMID 36776316, 2023). "We analyzed the expression of TSHR in thyroid cancer tissues using the TCGA database." (PMID 38174330, 2023).